TSGA13 (testis specific 13)
Tractability: Antibody: the Human Protein Atlas places it where antibodies can reach.
Gene: Protein-coding gene on chromosome 7 (130,668,643 to 130,687,432, reverse strand). Ensembl gene ENSG00000213265.
Subcellular location (Human Protein Atlas): Vesicles; Cytosol; Plasma membrane
Gene Ontology:
Molecular function: protein binding
Genetic constraint (gnomAD): Loss-of-function variants: 37 observed, 36.14 expected, observed/expected ratio (o/e) 1.02, 90% interval 0.79 to 1.35. The upper end of that interval is the gene's LOEUF score, 1.35, which puts it in group 5 of 6, group 1 being the genes least tolerant of losing a copy. Missense variants: 338 observed, 340.28 expected, observed/expected ratio (o/e) 0.99, 90% interval 0.91 to 1.09. Synonymous variants: 124 observed, 126.36 expected, observed/expected ratio (o/e) 0.98, 90% interval 0.85 to 1.14.
Homologues: Orthologues: chimpanzee TSGA13 (99% identical), chimpanzee TSGA13 (98% identical), macaque TSGA13 (94% identical), pig TSGA13 (68% identical), rabbit TSGA13 (67% identical), dog TSGA13 (65% identical), guinea pig TSGA13 (59% identical), mouse Tsga13 (59% identical), rat Tsga13 (57% identical).